KEAP1 (kelch like ECH associated protein 1)
Diseases named in the same sentence as KEAP1 in open-access papers (continued):
Sharing a sentence is not in itself a finding about the gene and the disease.
leukemia (9 papers, 2018 to 2025). A malignant (clonal) hematologic disorder, involving hematopoietic stem cells and characterized by the presence of primitive or atypical myeloid or lymphoid cells in the bone marrow and the blood. "Moreover, treatment with venetoclax/HMA reversed decitabine-induced nuclear translocation of NRF2, expression of downstream antioxidant enzymes and BCL2-binding to NRF2/kelch-like ECH-associated protein 1 (KEAP-1) complex, resulting in an anti-leukemia activity." (PMID 40603833, 2025). "Given that ATO was primarily used in hematological malignance instead of another disease, we first assessed the KEAP1 expressions in leukemia patients from the TARGET database, which contained genetic characteristics and clinical information of pediatric acute ALL patients." (PMID 37251921, 2023). "As anticipated, DFX administration also yielded a significant augmentation in the mRNA levels of genes pertinent to ferroptosis, namely, NRF2, KEAP1, HO-1, GPX4, and SLC7A11, within the leukaemia cells of individuals with ALL." (PMID 38671872, 2024). "By contrast, Zn supplementation (3d) of human leukemia monocytic THP-1 cells has negligible effects on NRF2 and Keap1 mRNA expression." (PMID 37315344, 2023). "Somatic mutations in KEAP1 and NRF2 occur in a variety of cancer types and are important mediators of aberrant anti-oxidant responses; however, no such mutations have been reported to date in human leukemia cells (The Cancer Genome Atlas, TCGA, database)." (PMID 29545928, 2018). "However, a specific role for the Keap1/Nrf2 axis in the induction of autophagy in leukemia has not been shown." (PMID 29545928, 2018).
metabolic syndrome (9 papers, 2013 to 2026). A cluster of metabolic risk factors for CARDIOVASCULAR DISEASES and TYPE 2 DIABETES MELLITUS. "Lastly, we described the Pearson correlation analysis of ALP-dependent Keap1-Nrf2 signaling pathway-induced antioxidants with LPS/ROS-induced gut barrier dysfunctions, systemic inflammation, growth performance, and metabolic syndrome." (PMID 38003191, 2023). "In this review we will discuss the recent research results on the role of the Keap1/Nrf2 pathway in metabolic regulation and suggest the potential manipulation of this pathway for the prevention and treatment of metabolic syndrome." (PMID 23363332, 2013). "LPS, ROS, MDA, and Keap1 were significantly positively correlated with inflammatory cytokines (IL-1β, COX2, TNF-α, IL-6, and iNOS), metabolic syndrome (LDL-C, T-CHO, TG, and BUN), ABW, and ADG at 45 d, 60 d, and 90 d of sample collection." (PMID 38003191, 2023). "Nrf2/Keap1 signaling pathway is a key regulator of oxidative stress and repressor of lipogenesis, which plays a vital role in MAFLD-related metabolic syndrome and oxidative stress." (PMID 34822647, 2021). "Indirect genetic activation of NRF2 achieved by KEAP1 deletion confers protection from short-term HFD-induced metabolic dysfunctions, while chronic long-term NRF2 activation results in increased weight gain and elevated markers of the metabolic syndrome." (PMID 35323110, 2022). "Herein, we sought to evaluate whether orlistat could improve metabolic syndrome and oxidative stress in HFD-induced MAFLD rats and activate Nrf2/Keap1 signaling pathway to exert its protective and therapeutic effects." (PMID 34822647, 2021). "Besides, DPDS not only improved dyslipidemia in STZ diabetic rats, but also enhanced the activities of antioxidant enzymes, decreased the level of MDA in serum and kidney, and regulated the expression of proteins related to the Nrf2/Keap1 signaling pathway in the kidney." (PMID 39697537, 2024).
metastatic disease (9 papers, 2015 to 2025). "In the pooled dataset of 282 spine metastatic tumors, KEAP1 was mutated in 6% of samples and was predictive of poor survival." (PMID 40647516, 2025). "A patient with a PD-L1-negative, TMB-low, KEAP1/STK11 co-mutated metastatic non-small cell lung cancer (NSCLC) experienced a multisite radiological progression at 3 months after initiation of chemoimmunotherapy as first-line treatment for metastatic disease." (PMID 39170614, 2024). "Given the intrinsic link between the Keap1/Nrf2 pathway and metastatic possibility, it is likely that metastatic tumors harboring Keap1/Nrf2 mutations in HN-CSCs may pose multiple risks of distant metastatic disease." (PMID 37894373, 2023). "Patients with single or co-occurring STK11 and KEAP1 mutations had similar distributions in sex and primary versus metastatic tumor status compared with the mutation-negative group." (PMID 40427178, 2025). "Notably, our genomic alteration in metastatic tumor data shows that KEAP1 mutations are enriched in BRAF Class 2 NSCLCs, suggesting that cooperation between Class 2 BRAF mutations and KEAP1 loss-of-function mutations may promote cancer progression." (PMID 38275886, 2024). "No inverse correlation between CpGs methylation and KEAP1 protein levels was found in either the LUAD or the LUSC cohort (all-stage and non-metastatic disease stages)." (PMID 32971994, 2020).
myocardial infarction (9 papers, 2021 to 2025). Gross necrosis of the myocardium, as a result of interruption of the blood supply to the area, as in coronary thrombosis. "Urolithin B, a gut microbiota metabolite, was reported to decrease the myocardial infarct size and attenuate cardiac dysfunction via the p62/Kelch like ECH associated protein 1 (Keap1)/NRF2 signaling pathway." (PMID 37927531, 2023). "We previously reported that miR-432-5p has a protection effect on myocardial infarction through activating Nrf2 pathway by degrading Keap1 via direct interaction." (PMID 39177670, 2024). "In conclusion, miR-432-5p inhibits the ferroptosis in cardiomyocytes induced by H/R by activating Nrf2/SLC7A11 axis by degrading Keap1 and is a potential drug target for clinical myocardial infarction treatment." (PMID 37822721, 2023). "Nrf2/Keap1/ARE is an important signalling pathway that reduces the area of myocardial infarction and protects heart function after MIRI." (PMID 36195952, 2022). "Additionally, a circular RNA, circPVT1, protects the myocardium from myocardial infarction (MI) and hypoxia/reoxygenation (H/R) injury by miR-125b/miR-200 sponges and then regulating Keap1/Nrf2- and Pdcd4-mediated apoptotic signaling." (PMID 34917083, 2021). "However, in the setting of ageing and myocardial infarction (MI), EVs from aged mesenchymal stem cells (MSC‐EVs) exhibit a downregulation of miRNA‐200a, leading to the restoration of Keap1 expression." (PMID 40916911, 2025).
Stroke (9 papers, 2018 to 2025). Sudden impairment of blood flow to a part of the brain due to occlusion or rupture of an artery to the brain. "Although these reagents need to be further studied in the stroke model, it is undeniable that preventing Nrf2 from being degraded by proteasome through modification or inhibition of Keap1 is a promising measure in the protection of neurons after stroke." (PMID 35462700, 2022). "Obviously, preventing the proteasome degradation of Nrf2 through the regulation of Keap1 is very important for neuroprotection after stroke." (PMID 35462700, 2022). "It has been shown that the Keap1- Nrf2-ARE signaling pathway is involved in the protective effect of stroke on brain tissue." (PMID 36558549, 2022). "Nuclear factor erythroid 2-related factor 2 (Nrf2) was one of the novel targets in the treatment of stroke due to its ability to induce the antioxidative potential of the cell especially in neurons by cooperating with its actin-binding protein Keap1." (PMID 36079918, 2022). "Intense oxidative stress stimulates the ROS scavenging mechanisms, and the marked downregulation of circ_Gucy1a2_7 and circ_Ryr2_36 by more than 4-fold after stroke may lead to the release of adsorbed miR-7a-5p and the consequent downregulation of Keap1 at the posttranscriptional level." (PMID 34868302, 2021).
thyroid cancer (9 papers, 2013 to 2025). "Remarkably, we identified KEAP1 mutations in all thyroid cancer histologies, ranging from well-differentiated forms (PTC, FTC) to PDTC and ATC, with no subtype-specific mutational pattern." (PMID 41573641, 2025). "We also report the first functional characterization of KEAP1 mutations in thyroid cancer using in vitro models." (PMID 41573641, 2025). "cBioPortal analysis indicated that mutations in the genes encoding p62, Keap1, and Nrf2 were present in these patients, and 15% of patients with thyroid cancer exhibited mutations in SOSTM1, KEAP1, or NFE2L2." (PMID 41394539, 2025). "Our novel in vitro findings highlight the clinical relevance of KEAP1 mutations in thyroid cancer and underscore the importance of mutational profiling to better inform therapeutic strategies." (PMID 41573641, 2025). "Given that the abnormal activation of Nrf2 is associated with thyroid cancer progression and chemoresistance, targeting the Keap1‐Nrf2 pathway is considered a promising anticancer strategy." (PMID 41394539, 2025). "Our comprehensive report of KEAP1 mutations in thyroid tumors highlights its previously unappreciated prevalence and broad distribution across thyroid cancer subtypes." (PMID 41573641, 2025). "We examined sequencing data from publicly available datasets and published literature, and identified an additional 75 tumor samples and two thyroid cancer cell lines with KEAP1 mutations." (PMID 41573641, 2025). "Although prior reports have only identified a small number of KEAP1 mutations in PTCs and benign MNGs, we identified 81 such alterations across a diverse spectrum of thyroid cancers." (PMID 41573641, 2025). "By combining multi-omic analyses with in vitro characterization of KEAP1 loss in thyroid cancer, we demonstrate that these mutations are functionally relevant and capable of promoting tumorigenesis across diverse genetic landscapes." (PMID 41573641, 2025). "Here, we report the first instance of KEAP1 mutations attenuating drug response in thyroid cancer cells." (PMID 41573641, 2025). "This potential dual role—as either an initiating event or cooperating alteration—highlights the previously unrecognized importance of KEAP1 mutations in thyroid cancer." (PMID 41573641, 2025). "This study is also the first to comprehensively explore the functional consequences KEAP1 loss in thyroid carcinoma." (PMID 41573641, 2025). "While KEAP1 mutations have been well documented in various cancers, their presence and role in thyroid carcinoma have remained largely unexplored." (PMID 41573641, 2025). "In order to characterize the molecular mechanisms leading to Nrf2 activation in thyroid carcinoma, mutations in the Keap1/Nrf2 pathway were sought." (PMID 31428048, 2019). "Having observed KEAP1 mutations in a number of pediatric thyroid cancer cases, we sought to determine whether they promote thyroid tumorigenesis, as has been reported in other malignancies." (PMID 41573641, 2025). "We therefore investigated whether KEAP1 loss modulates the sensitivity of thyroid cancer cells to targeted RET inhibition." (PMID 41573641, 2025). "The Western blot results revealed that IDET considerably decreased p62 protein expression in thyroid cancer cells while increasing Keap1 protein expression, and these effects were accompanied by low Nrf2 protein levels in the cytoplasm and nucleus." (PMID 41394539, 2025). "While these previous reports identify KEAP1 mutations and implicate the KEAP1-NRF2 pathway in thyroid cancer, this connection has remained incompletely characterized." (PMID 41573641, 2025). "We proceeded to analyze mutations in the SOSTM1, KEAP1, and NFE2L2 genes in patients with thyroid cancer." (PMID 41394539, 2025). "We show that loss of KEAP1 reduces sensitivity of RET fusion-positive PTC cells to the receptor tyrosine kinase inhibitor selpercatinib, a key therapeutic agent for RET-driven thyroid cancers." (PMID 41573641, 2025).
thyroid cancer (continued). "This review summarizes the recent work on Keap1/Nrf2 signaling in thyroid physiology, and pathophysiology in general and in thyroid cancer in particular." (PMID 31428048, 2019). "This review focuses on the involvement of Keap1/Nrf2 signaling in thyroid physiology, and pathophysiology in general, and particularly in thyroid cancer." (PMID 31428048, 2019). "Notably, qRT‐PCR analysis showed that IDET considerably upregulated the expression of KEAP1 and NFE2L2 mRNAs in thyroid cancer cells, where Nrf2 is encoded by NFE2L2." (PMID 41394539, 2025). "This study demonstrates that desirable effects on thyroid carcinoma might be achieved not only by targeting Nrf2 directly, but also potentially by targeting other components of the Keap1/Nrf2 pathway and its downstream signaling." (PMID 31428048, 2019). "These considerations suggest that the Keap1/Nrf2 pathway, as a key regulator of antioxidant defenses, may play important roles in the pathophysiology of thyroid carcinomas." (PMID 31428048, 2019). "Occasional NFE2L2 and KEAP1 mutations were recently identified as part of whole-exome sequencing analysis of patient cohorts with Hürthle-cell (oncocytic) thyroid carcinoma (HCC), a type of differentiated thyroid carcinoma characterized by cells with abundant but dysfunctional mitochondria." (PMID 31428048, 2019).
cervical cancer (8 papers, 2015 to 2025). A primary or metastatic malignant neoplasm involving the cervix. "In summary, strong nuclear expression of NRF2 was significantly associated with reduced cytoplasmic Keap1 expression in cervical cancers due to hypermethylation." (PMID 26247201, 2015). "In addition, we evaluated the expression of NRF2 and Keap1 in 89 cases of cervical cancer and examined associations with pathologic features and clinical outcomes." (PMID 26247201, 2015). "In addition, this is the first report to show an association between NRF2/Keap1 staining and clinicopathological features in cervical cancer." (PMID 26247201, 2015). "Epigenetic changes, such as hypermethylation of the KEAP1 gene promoter, are also associated with increased NRF2 activity in cervical cancer." (PMID 41333220, 2025). "In cervical carcinoma, KEAP1 expression is significantly decreased in the cytoplasm of cancer cells compared with that of normal cervical epithelial cells, which increases NRF2 activity." (PMID 35163828, 2022). "The promoter hypermethylation of Keap1 significantly increased nuclear NRF2 expression in cervical cancer tissues, which is a marker of poor prognosis in patients with cervical cancer." (PMID 29850477, 2018). "We demonstrated that Keap1 was frequently hypermethylated with reduced expression in cervical cancer cells." (PMID 26247201, 2015). "This is the first report of increased Keap1/NRF2 signaling as a result of KEAP1 hypermethylation in cervical cancer." (PMID 26247201, 2015). "Methylated CpG islands in the Keap1 gene promoter in cervical cancer tissue were identified using MassARRAY." (PMID 26247201, 2015). "Further, nuclear translocation of NRF2 may occur through a Keap1-independent pathway in cervical cancers." (PMID 26247201, 2015). "To determine the role of the Nrf2/Keap1 signaling cascade in cepharanthine-induced oxidative stress, we analyzed the protein expression patterns of Nrf2, Keap1, NQO1, and HO-1 in cepharanthine-treated cervical cancer cells using Western blot analysis." (PMID 41300481, 2025). "Studies have shown that cervical cancer tissues often exhibit increased nuclear NRF2 expression and decreased cytoplasmic KEAP1 expression." (PMID 41333220, 2025). "Thus, the NRF2/Keap1 system may be dysregulated in human cervical cancers." (PMID 26247201, 2015). "However, the methylation status of KEAP1 in cervical cancer is unknown." (PMID 26247201, 2015). "We show here that NRF2 activation increases the expression of TIGAR in the cervical cancer HeLa cell line both in response to NRF2 overexpression and following exposure to the electrophilic molecules SFN and DMF, which induce the dissociation of NRF2 from KEAP1." (PMID 35163828, 2022).
esophageal cancer (8 papers, 2018 to 2025). A primary or metastatic malignant neoplasm involving the esophagus. "The patient case with anaplastic thyroid cancer was not tested for the KEAP1 mutation, while the patient case with esophageal cancer was confirmed to harbor the KEAP1 mutation." (PMID 39373520, 2025). "Loss-of-function mutations in KEAP1, degradation-resistant NRF2 mutations, and defective mutations of ubiquitin ligase CUL3 have been reported in lung or esophageal cancer cells." (PMID 35053572, 2022). "While 2 family members with different KEAP1 mutations had anaplastic thyroid and esophageal cancers (Q86* I-4 and L136P III-1), respectively, no frequent complications were detected in this study, suggesting a predisposition to thyroid-specific phenotypes by KEAP1 germline heterozygous mutations." (PMID 39373520, 2025).
gallbladder cancer (8 papers, 2011 to 2025). "Non-conservative amino acid substitutions in KEAP1 gene have been reported also in lung, breast and gallbladder cancers, resulting in a non-functional protein and, consequently, in alterations in the KEAP1/NRF2 axis." (PMID 34141616, 2021). "Interestingly, however, a recent study has revealed that siRNA depletion of Nrf2 in TGBC24TKB gall bladder cancer cells, in which Keap1 is not expressed and Nrf2 is constitutively present at high levels, can increase sensitivity to 5FU." (PMID 21489257, 2011).
glioblastoma (8 papers, 2017 to 2026). The most malignant astrocytic tumor (WHO grade IV). "In the U-87 MG and U-373 MG glioblastoma lines, a pool of KEAP1 was localized in at the perinuclear cytoplasm, and another was close to the plasma membrane clustered in the podosomes, invadosomes, or other Actin-rich structures." (PMID 32825452, 2020). "Constitutive activation of the transcription factor NRF2 confers therapeutic resistance in glioblastoma (GBM), however, this hyperactivation frequently persists despite the presence of intact KEAP1, suggesting the existence of KEAP1-independent regulatory mechanisms." (PMID 41926909, 2026). "Fisetin and quercetin did not markedly change the protein levels of HMGB1, HSP72, or KEAP1 in microglia and glioblastoma, but did modulate key protein–protein interactions." (PMID 38132142, 2023). "Interestingly, in glioblastoma cells, chrysin suppressed the expression of the Nrf2 protein and its major target genes as well as disrupting the ERK/Nrf2 signaling pathway without inducing kelch-like ECH-associated protein 1 (Keap-1) protein levels, the Nrf-2 negative modulator." (PMID 36613834, 2022).